SNHG15 (small nucleolar RNA host gene 15)
Diseases named in the same sentence as SNHG15 in open-access papers (continued):
Sharing a sentence is not in itself a finding about the gene and the disease.
non-small cell lung carcinoma (5 papers, 2020 to 2021). A group of at least three distinct histological types of lung cancer, including non-small cell squamous cell carcinoma, adenocarcinoma, and large cell carcinoma. "Small nucleolar RNA host gene 15 (SNHG15) has been shown to provide a potential therapeutic effect through the regulation of CDK14 protein by sponging miR-486 in non-small-cell lung cancer (NSCLC) patients." (PMID 34079751, 2021). "Similarly, in non-small cell lung cancer, two studies have demonstrated that SNHG15 knockdown suppresses tumorigenesis by inhibiting the expression of EMT, MMP2, and MMP9 and regulating the miR-486/CDK14 axis." (PMID 33243205, 2020).
medulloblastoma (3 papers, 2021 to 2023). A malignant, invasive embryonal neoplasm arising from the cerebellum. "The pro-oncogenic and pro-migratory function of SNHG15 is in line with the ephrinA5-Fc-induced downregulation of Snhg15 in CB cells, which are commonly used as a medulloblastoma cell model, as well as the observed motility restriction." (PMID 37880732, 2023). "As Snhg15 is a cancer-related lncRNA, and CB cells serve as a model for medulloblastoma, these findings might have impact on tumor cell biology since the Eph/ephrin system is critically involved in cancer trajectories." (PMID 37880732, 2023). "An ephrinA5-Fc triggered reduction in SNHG15 was further observed in DAOY cells, a human medulloblastoma cell line." (PMID 33572758, 2021).
pancreatic adenocarcinoma (3 papers, 2020 to 2023). "SNHG15 is a lncRNA involved in tumor malignancy behavior and has been indicated to be a potential biomarker for pancreatic adenocarcinoma diagnosis and prognosis." (PMID 37189687, 2023).
diabetes (2 papers, 2023 to 2025). "Previous studies have shown that the expression of Snhg15 decreases in the hind limbs of mice with diabetes." (PMID 41144575, 2025). "Nevertheless, studies indicated molecular crosstalk between TXNIP and Snhg15 during diabetes." (PMID 41144575, 2025). "Our findings showed that Snhg15 may be a novel biomarker of spinal cord dysfunctions during diabetes." (PMID 41144575, 2025). "Overall, Snhg15 overexpression may improve endothelial function during diabetes and thus erase the negative effect of TXNIP in the spinal cord of mice." (PMID 41144575, 2025).
Hyperglycemia (2 papers, 2023 to 2025). An increased concentration of glucose in the blood. "We found that in prolonged hyperglycemia the expression of Snhg15 lncRNA was elevated in the spinal cord of T1D mice." (PMID 41144575, 2025). "We speculate that elevated expression of SNHG15 may be compensatory to overexpression of TXNIP in lumbar SC in hyperglycemia." (PMID 37462767, 2023).
ischaemic stroke (2 papers, 2022 to 2023). "This indicated that an important function for SNHG15 in controlling the initiation and development of ischaemic stroke was demonstrated." (PMID 37845831, 2023). "SNHG15 markedly impaired inflammatory responses through interference with TRAF2 auto-ubiquitination in the acute stage of ischemic stroke." (PMID 34980176, 2022). "SNHG15/miR‐153‐3p/ATG5 axis was possible pathway and target in treatment of ischaemic stroke." (PMID 37845831, 2023). "First, we could not find any evidence of SNHG15/miR‐153‐3p/ATG5 gene or protein production in those who had had an ischaemic stroke." (PMID 37845831, 2023).
mesothelioma (2 papers, 2020 to 2025). A usually malignant and aggressive neoplasm of the mesothelium which is often associated with exposure to asbestos. "Additionally, we identified other lncRNAs enriched in PM-EVs, such as SNHG9, SNHG11 and SNHG15, which have been previously associated with cancer development and were associated with mesothelioma patients’ survival in our analysis." (PMID 39920655, 2025). "Furthermore, increased SNHG15 expression was correlated with worse OS in adrenocortical carcinoma (ACC), KIRC, mesothelioma (MESO), uveal melanoma (UVM), and worse DFS in ACC, prostate adenocarcinoma (PRAD), UVM (log-rank P < 0.05)." (PMID 33243205, 2020).
osteoarthritis (2 papers, 2023 to 2024). A noninflammatory degenerative joint disease occurring chiefly in older persons, characterized by degeneration of the articular cartilage, hypertrophy of bone at the margins and changes in the synovial membrane. "Small nucleolar RNA host gene 15 (SNHG15) plays an important role in the regulation of osteoarthritis and may be a potential target for OA therapy." (PMID 38259516, 2023).
atherosclerosis (1 paper, 2024). A disease characterized by the build-up of fatty material and calcium deposition in the arterial wall resulting in partial or complete occlusion of the arterial lumen. "Among the downregulated lncRNAs, eight had at least one citation; AI662270, AU020206, and Snhg15 were of particular interest, as it has been reported that AI662270 and AU020206 are involved in the atherosclerosis induced by macrophages and Snhg15 is involved in inflammation." (PMID 38711507, 2024).
autoimmune disorders (1 paper, 2025). "LINC00963, SNHG15, and SNHG3 are lncRNAs that have garnered attention for their roles in cancer and autoimmune disorders." (PMID 39969652, 2025). "Notably, the up-regulation of lncRNAs such as LINC00963, SNHG15, and SNHG3 underscores their significant involvement in inflammatory cascades and highlights their potential utility as biomarkers or therapeutic targets in autoimmune diseases." (PMID 39969652, 2025).
brain injuries (1 paper, 2023). "Furthermore, they analyzed the SNHG15/miR-153-3p/SETD7 axis and demonstrated that the suppression of SNHG15 alleviated HI brain injuries by modulating this axis." (PMID 38002304, 2023).
breast tumors (1 paper, 2024). "SNHG15 expression is positively associated with larger tumor sizes and the lymph-node metastasis of breast tumors." (PMID 39519115, 2024). "Since the sample size in our study was relatively small, future studies are necessary to collect and use large population sizes to confirm the corelative expression of SNHG15 and MTSS1 mRNA in human breast tumors." (PMID 39519115, 2024).
Cerebral ischemia (1 paper, 2021). Restriction of arterial blood supply to the brain associated with insufficient oxygenation to support the metabolic requirements of the tissue. "This study aims to assess the mechanism of SNHG15 in the occurrence and development of cerebral ischemia/reperfusion injury of nerve cells and to investigate its potential value for diagnosis and treatment." (PMID 34868528, 2021).
colorectal adenocarcinoma (1 paper, 2019). The most common type of colorectal carcinoma. "Interestingly, the classification of colorectal adenocarcinoma TCGA samples relative to MYC expression showed that SNHG15 is upregulated in the samples with high levels of MYC expression." (PMID 31014355, 2019). "In order to investigate the transcriptional regulation of SNHG15 by MYC, we analyzed colorectal adenocarcinoma RNA-seq data from TCGA, finding that SNHG15 is significantly upregulated in the tumors with high level of MYC expression." (PMID 31014355, 2019).
endothelial dysfunction (1 paper, 2021). In vascular diseases, endothelial dysfunction is a systemic pathological state of the endothelium (the inner lining of blood vessels) and can be broadly defined as an imbalance between vasodilating and vasoconstricting substances produced by (or acting on) the endothelium. "Indeed, a recent report showed that high glucose-treated HUVEC downregulate lnc-SNHG15, which reduces TXNIP expression by enhancing its ubiquitination, thus mitigating high glucose-induced endothelial dysfunction." (PMID 34944690, 2021).
kidney cancer (1 paper, 2023). Primary or metastatic malignant neoplasm involving the kidney. "Meanwhile, the migration and invasion ability of kidney cancer was enhanced by TNF-α stimulation, whereas the knockdown of SNHG15 attenuated this effect." (PMID 37056344, 2023).
Lymphatic Metastasis (1 paper, 2020). Transfer of a neoplasm from its primary site to lymph nodes or to distant parts of the body by way of the lymphatic system. "In addition, high SNHG15 expression level was significantly correlated with later TNM stage (OR = 3.05, 95% CI = 2.31–4.02, P < 0.00001), lymphatic metastasis (OR = 3.20, 95% CI = 2.30–4.45, P < 0.00001), and distant metastasis (OR = 5.05, 95% CI = 2.15–11.85, P=0.0002)." (PMID 32733556, 2020).
myeloma (1 paper, 2024). "Our study suggested a novel epigenetically interaction of N6-methyladenosine (m6A) methylation, lncRNA SNHG15, and histone SETD2/H3K36me3 modifications in myeloma progression, indicating that ALKBH5 and lncRNA SNHG15 could serve as potential novel therapeutic targets for MM treatment." (PMID 38145297, 2024).
Nephroblastoma (1 paper, 2024). An embryonal neoplasm characterized by the presence of epithelial, mesenchymal, and blastema components. "SNHG15 has been found to be an immune-associated prognostic biomarker in patients with nephroblastoma." (PMID 38526609, 2024). "The expression level of SNHG15 in nephroblastoma was higher than that in normal kidney tissues, and there was a significant difference (t = 2.934, P = 0.006)." (PMID 38526609, 2024). "SNHG15 may promote M2 macrophage infiltration in nephroblastoma, which is potentially valuable in predicting prognosis and improving therapeutic efficacy, especially immunotherapy." (PMID 38526609, 2024). "Finally, more in vitro and in vivo experiments are needed to validate the specific role and mechanism of SNHG15 in nephroblastoma." (PMID 38526609, 2024). "In an attempt to further verify the function of SNHG15, an independent data set (GSE66405) was selected to verify the expression of SNHG15 in nephroblastoma." (PMID 38526609, 2024).
type 2 diabetes (1 paper, 2023). "In conclusion, SNHG15 is a negative regulator of inflammation, and its expression is downregulated in patients with type 2 diabetes, which may be related to the high level of inflammation in type 2 diabetes." (PMID 37153000, 2023).
cancer (44 papers, 2019 to 2025). A tumor composed of atypical neoplastic, often pleomorphic cells that invade other tissues. "We demonstrated earlier that ephrinA5-Fc stimulation of CB cells modulates the expression of protein-coding genes as well as of non-coding RNAs, including the cancer-associated lncRNA Snhg15." (PMID 37880732, 2023). "Its human ortholog SNHG15 has cancer- and metastasis-promoting functions, linked to poor survival in numerous human malignancies." (PMID 37880732, 2023). "Over the past few years, SNHG15 has been identified for its fundamental role in regulating oncogenes and tumor suppressors, as well as the underlying cancer characteristics." (PMID 37056344, 2023). "When SNHG15 is produced in higher quantities, it is associated with tumorigenic functions, including proliferation and metastasis in a variety of cancer types." (PMID 35629174, 2022). "We also evaluated the TCGA cohort to confirm the prognostic role of SNHG15 in various cancers, and the elevated expression of SNHG15 in 33 types of tumour tissues was associated with worse OS and DFS." (PMID 33243205, 2020). "Twelve studies with 1058 enrolled patients explored the association between the expression level of SNHG15 and the overall survival in various cancers." (PMID 32633324, 2020). "Interestingly, literature mining revealed that three lncRNAs (XXbac-B476C20.9, TP73-AS1, and SNHG15) had been confirmed to be significantly associated with cancer." (PMID 36118850, 2022). "To further demonstrate whether SNHG15 could serve as a prognostic predictor in various cancers, we explored the association between elevated SNHG15 expression and survival indicators (OS/DFS)." (PMID 33243205, 2020). "Furthermore, the high expression of SNHG15 is associated with poor prognosis of patients with different types of cancer." (PMID 32733556, 2020). "Moreover, several genes deregulated after SNHG15 depletion are implicated in cancer initiation, progression and also survival pathways." (PMID 31014355, 2019). "Furthermore, SNHG15 has been well-documented to be an effective diagnostic and prognostic marker for tumors, offering novel therapeutic interventions in specific subsets of cancer cells." (PMID 37056344, 2023). "The results showed that high expression level of SNHG15 was associated with shorter overall survival in digestive, respiratory and female reproductive system cancers, and supported the positive association between high expression level of SNHG15 and poor prognosis in various cancer types." (PMID 32633324, 2020). "For example, SNHG15 and LINC00963 have been implicated in cancer and other inflammatory conditions, raising concerns about their specificity for RA diagnosis." (PMID 39969652, 2025). "This interactome aligns with observations that suppression of SNHG15 leads to cell cycle arrest in cancer models." (PMID 41369348, 2025). "After that, the functional mechanisms, immunological and molecular characterization of SNHG15 were investigated at the scRNA-seq, pan-cancer, and RNA-seq levels using Gene ontology (GO), Kyoto Encyclopedia of Genes and Genomes (KEGG), ESTIMATE, and CIBERSORT." (PMID 38526609, 2024). "Generally, SNHG15 facilitated the survival of malignant cells by promoting autophagy and was a promising target for anti-cancer treatments in patients against sensitive malignant cells." (PMID 37056344, 2023). "SNHG15 participates in initiation and progression of diverse cancer types by affecting proliferation and migration." (PMID 37880732, 2023). "SNHG15 exerted oncogenic or tumor-suppressive effects in cancer through multiple molecular mechanisms." (PMID 37056344, 2023). "We provide evidence that Snhg15, a cancer-related lncRNA, recruits DNMT1 to the Ncam1 promoter through RNA/DNA triplex structure formation and the interaction with DNMT1." (PMID 37880732, 2023).
cancer (continued). "This review summarized the current understanding of SNHG15 in cancer, mainly focusing on the pathological features, known biological functions, and underlying molecular mechanisms." (PMID 37056344, 2023). "Multiple studies have declared that the up-regulation of SNHG15 has significant clinical significance and was expected to serve as a promising biomarker for early cancer diagnosis and prognosis." (PMID 37056344, 2023). "SNHG15 is highly expressed in colon cancer cells, especially in cancer cells with high MYC expression." (PMID 37020597, 2023). "When SNHG15 is knocked out by siRNA or CRISPR/Cas9, the tumor-causing ability and proliferation and invasion ability of cancer cells were reduced, and the sensitivity to 5-FU was enhanced." (PMID 37020597, 2023). "We found dysregulated expression of lncRNAs such as Snhg15, an important cancer-related lncRNA, in response to ephrinA5-Fc treatment." (PMID 37880732, 2023). "The lncRNA SNHG15 has recently been revealed to be dysregulated in malignant tumors, suggesting the aberrant expression of which contributes to clinical features and regulates various oncogenic processes." (PMID 37056344, 2023). "High expression of SNHG15 in cancer tissue samples exerted an extremely promising potential to predict the adverse prognosis of cancer patients." (PMID 37056344, 2023). "Based on the role of SNHG15 in cancer progression, more investigation of the mechanisms by which SNHG15 mediates oncogenic processes is necessary to better understand its function and provide essential insight in the clinical treatment of cancer patients." (PMID 37958584, 2023). "The present results provided compelling evidence that SNHG15 functioned as an active regulator of cell cycle G1/S transition to promote cancer cell growth in vitro and in vivo." (PMID 37056344, 2023). "Small nucleolar RNA host gene 15 (SNHG15) is a lncRNA whose dysregulation has been found to have an important impact on carcinogenesis and affect the prognosis of cancer patients in various cancer types." (PMID 35629174, 2022). "Emerging research has revealed that PVT1 and SNHG15 play important roles in the progression of various cancers, including KIRC." (PMID 36052236, 2022). "All findings suggested that SNHG15 was promising as a biomarker and therapeutic target for cancer patients." (PMID 35910212, 2022). "A query to the lnc2Cancer database showed that eight of the 14 differential hub lncRNAs (LINC00909, BZRAP1-AS1, C17orf76-AS1, HCG11, MIAT, SNHG5, SNHG15, and TP73-AS1) were associated with various types of carcinomas in previous studies." (PMID 35432537, 2022). "SNHG15 is an lncRNA which plays critical roles in the development and progression of various cancers through regulation of Akt/mTOR signaling." (PMID 34439315, 2021). "An important lncRNA, which has been associated with proliferation and migration regulation in different human cancer tissues, is the small nucleolar RNA host gene 15 (SNHG15)." (PMID 33572758, 2021). "Snhg15 is known to be involved in proliferation and migration regulation in various human cancer types." (PMID 33572758, 2021). "Thereby, SNHG15 was reported to have both cancer- and metastasis-promoting and also tumor-suppressing functions, suggested to be linked with poor survival in numerous human malignancies." (PMID 33572758, 2021). "Although SNHG15 has been described to serve as a competitively endogenous RNA (ceRNA) sponging miRNA in human cancers, it was also reported that SNHG15 is seen at much higher levels in the nucleus than in the cytoplasm." (PMID 33572758, 2021). "Hence, transcriptional control by Snhg15 via triplex structure formation with distinct promoters might be an additional mechanism through which Snhg15 could be involved in transcriptional regulation of underlying cancer-related processes." (PMID 33572758, 2021). "A significant correlation was revealed between the high expression level of SNHG15 and poor prognosis in various cancer types." (PMID 32633324, 2020).